DISC1 (DISC1 scaffold protein)
Diseases named in the same sentence as DISC1 in open-access papers (continued):
Sharing a sentence is not in itself a finding about the gene and the disease.
psychiatric disorder (continued). "Given the preferential expression of DISC1 in the hippocampus and the involvement of this brain structure in cognition and psychiatric disorders, we set out to determine the impact of DISC1 on synaptic vesicle (SV) cycling in hippocampal neurons." (PMID 27378904, 2016). "The relevance of DISC1 to mental illness in the wider population remains a matter for fierce debate, but functional studies have demonstrated that DISC1 has important roles in embryonic and adult neurogenesis." (PMID 26405049, 2015). "Studies of a family in Scotland over several decades revealed that a gene called DISC1 was shortened in family members who had been diagnosed with mental illnesses." (PMID 25735038, 2015). "The numerous animal models that have been generated to investigate the role of DISC1 in the neurobiology of mental illness have been reviewed in considerable detail elsewhere." (PMID 25762938, 2015). "Our data show that Disc1 truncation induces translational endophenotypes in mice that are relevant to those seen in psychiatric diseases." (PMID 25989143, 2015). "Motivated by its potential role in psychiatric disease, several DISC1-related genetically modified mice have been generated in recent years." (PMID 24712988, 2014). "A striking negative effect on mitochondrial function was observed for novel DISC1 fusions, which involve part of the DISC1 protein coupled to a novel peptide sequence, possibly accounting for psychiatric disease in a large family." (PMID 25606056, 2014). "One of the tools to study the biology of DISC1 and its relevance to psychiatric disorders is mouse models in which this gene has been manipulated." (PMID 24027503, 2013). "Further, these molecules predominantly link to the DISC1 pathway, strengthening the evidence for the role of this gene network in the etiology of mental illness." (PMID 22363459, 2012). "Table of significant gene ontology terms that are biologically relevant to the DISC1 pathway or major mental illness." (PMID 19300510, 2009). "Disrupted in Schizophrenia 1 (DISC1) is a scaffold protein implicated in major mental illnesses including schizophrenia, with a significant negative impact on social life." (PMID 39194719, 2024). "We interrogated prefrontal circuit function in mice lacking Disrupted-in-schizophrenia-1 (Disc1-mutant mice), a risk factor for psychiatric disorders." (PMID 36239988, 2022). "Our results suggest that TRIOBP-1 aggregation, as defined by the high stringency protocol, identifies a substantial subset of mental illness patients as sharing a common disrupted biological process, potentially more so than can be identified by DISC1 aggregation." (PMID 36232351, 2022). "Notably, mutant DISC1 dysregulated expression of genes related to synapses, nervous system development, dendritic spine function pathways and psychiatric disorders in human forebrain neurons." (PMID 36527106, 2022). "A more recent study of iPSCs derived from SZ patients carrying a four base-pair deletion in Disrupted-in-schizophrenia 1 (DISC1), a gene that co-segregates with major psychiatric disorders, has reported aberrant synaptic formation and synaptic vesicle release deficits in patient-derived neurons." (PMID 31134525, 2020). "Here, we used the Disc1 LI mouse model to investigate the function of mPFC circuits that may be particularly relevant to the cognitive symptoms of psychiatric disorders." (PMID 32029441, 2020). "A number of studies have suggested that the aggregation of DISC1 might be important for psychiatric disease." (PMID 32066698, 2020). "DISC1 is one such gene that stands at the intersection of numerous psychiatric diseases." (PMID 30745562, 2019). "Moreover, functional studies showed that DISC1 contributes to the etiopathology of mental illness, including regulating neural progenitor proliferation, neurite outgrowth, neuronal migration, synapse formation, neurogenesis and cAMP signaling." (PMID 30233327, 2018).
psychiatric disorder (continued). "Further research is warranted to explore the roles of DISC1 and neurexin in psychiatric disease." (PMID 29079805, 2017). "DISC1 was first identified as a balanced translocation between chromosomes 1 and 11 (1q42.1; 11q14.8) in a Scottish pedigree with a high prevalence of schizophrenia and other psychiatric disorders." (PMID 27847649, 2016). "Future studies that integrate these findings into the broader context of DISC1 functioning may provide insight into the convergence of genetic disruptions in mental illness." (PMID 26656849, 2015). "In the future, a better understanding of the defects of inhibitory cells in DISC1 mutants and other mouse models of mental illness might open up new avenues for targeted drug design." (PMID 25735038, 2015). "Although implicated as a risk factor for psychiatric disorders, a consensus on the role of the DISC1 gene has not yet been reached." (PMID 26301809, 2015). "Genetic evidence implicates the DISC1 gene in the etiology of a number of mental illnesses." (PMID 22363459, 2012). "Our systematic analysis provides further evidence for the relevance of the DISC1 pathway to major mental illness, identifies additional potential targets for therapeutic intervention and establishes a general strategy to mine public datasets for insights into disease pathways." (PMID 19300510, 2009). "Furthermore, DISC1 is known to interact with other proteins of relevance to mental illnesses." (PMID 39194719, 2024). "Thus, two independent DISC1 mutations linked to major mental illness result in impaired neurite outgrowth via decreased expression of UNC5D, implicating this pathway in the pathogenesis of psychiatric disorders." (PMID 30410030, 2018). "Mutant DISC1 depleted wild-type DISC1 protein and, furthermore, dysregulated expression of many genes related to synapses and psychiatric disorders in human forebrain neurons, providing new insights into the molecular and synaptic etiopathology of psychiatric disorders." (PMID 29352035, 2018). "Thus, these mouse models that combine Disc1 mutation and MIA will become powerful models for understanding the molecular mechanisms underlying interactions between the gene and prenatal environmental factors that increase the risk of the psychiatric diseases." (PMID 26074774, 2015). "Taken together these findings strengthen evidence that DISC1 maintains a critical role in corpus callosum development and indicate that its involvement in the pathogenesis of psychiatric disorders may indeed be mediated through these structural white matter abnormalities." (PMID 26102360, 2015). "The overexpression of hflDISC1 in rats leads to the aggregation of the DISC1 protein and behavioral changes, which reflect similar aggregates seen in human patients with SCZ and other major mental illnesses." (PMID 39194719, 2024). "Controversy exists surrounding the relevance of DISC1 mutation to psychiatric disease given the lack of DISC1 association in large GWAS studies, and the limited number of pedigrees with DISC1 disruption and mental illness (two described to date with more than one carrier)." (PMID 30410030, 2018). "As the balanced translocation leads to elevated risk for mental illness in the heterozygous form (homozygous individuals have not been reported), we chose here to focus upon the model of DISC1 disruption most similar to the disease state, heterozygous exon 8 disruption (DISC1 ex8 wt/μ)." (PMID 29643329, 2018). "The gene-wide burden of non-synonymous coding changes was nominally, but not significantly increased in psychiatric disorders (unadjusted P=0.0048–0.0488) for several DISC1 Interactome genes." (PMID 28630456, 2018). "In addition to the evidence from the Finnish family cohort, the DISC1 and PDE4B genes are disrupted by chromosomal aberrations in Scottish families with major mental illness." (PMID 29142105, 2017).
psychiatric disorder (continued). "Thus, in this review, we will focus on the role of DISC1, DBZ (Sections 2 and 3), and SGK1 (Section 4) in oligodendrocytes and their relation to major psychiatric disorders, especially SZ and MDD." (PMID 25705664, 2015). "By comparison (48 cases), no major psychiatric disease was diagnosed in any of the relatives lacking DISC1 truncation." (PMID 25735038, 2015). "However, other studies, including recent genome-wide association studies, have not identified Disc1 as a risk factor for psychiatric disorders so although still of considerable interest in psychiatry, the role of Disc1 in such illnesses remains the subject of some debate." (PMID 24712988, 2014). "Thus, although the nature of the correlation needs further validation, the roles of DISC1 in the molecular clock may provide a novel mechanistic insight into the molecular links between SCRD and psychiatric disorders." (PMID 33542182, 2021). "Therefore, DISC1 and/or DBZ abnormalities are unlikely to be coincidental for some roles in the compromised white matter/myelin integrity of these psychiatric disorders." (PMID 25705664, 2015).
neurological disorders (10 papers, 2011 to 2022). "There are also possible GxE interactions between specific susceptible genotypes (e.g., genes linked to neurological disease such as Disc1) and infection as an environmental factor that need further exploration." (PMID 28513566, 2017). "Moreover, for nearly a decade, it was believed that DISC1 may resemble other protein risk factors in various neurological disorders, however, structural data at atomistic resolution have been severely lacking." (PMID 34921141, 2021). "Given the initial observation that schizophrenic patients exhibited a reduced spine density and the link between DISC1 and neurological disorders, it is pertinent that one of the most consistent observations made so far in many DISC1 mutants is a reduction in spine density." (PMID 30008190, 2018). "The potential link between DISC1, huntingtin and their interacting partners may open new areas of research into the effects of pathway dysregulation in severe neurological disorders." (PMID 21298101, 2011). "In addition, it is noteworthy that, surprisingly, an increased amount of insoluble DISC1 oligomer aggregates was detected in the postmortem brain of SCZ patients, demonstrating a common link with other neurological disorders characterized by protein aggregation such as AD and HD." (PMID 28331639, 2017).
cancer (6 papers, 2006 to 2023). A tumor composed of atypical neoplastic, often pleomorphic cells that invade other tissues. "We also investigated the role of DISC1 in cancer cell proliferation." (PMID 29029423, 2017). "Western blotting results showed that DISC1 and PCNA (a cancer cell proliferation marker) levels were higher in NSCLC tissues than in paired adjacent non-tumor tissues, and exhibited similar expression patterns." (PMID 29029423, 2017). "The other genes (SMARCE1, DISC1, CENTD2, RHOT1, ARHGAP6, ARHGEF9 and ARHGEF11) are also involved in cancer progression or chemoresistance." (PMID 23300757, 2012). "Three corresponded to genetic determinants of genetic syndromes (MTMR, DISC1, MTX1) and the three others bore functions with no obvious link to cancer (NENF, ENSA, TARBP1)." (PMID 17060936, 2006).
neurodegenerative disease (6 papers, 2014 to 2024). A disorder of the central nervous system characterized by gradual and progressive loss of neural tissue and neurologic function. "In light of these findings, we hypothesized that cell-to-cell spreading of aggregates, so far restricted to neurodegenerative diseases, could apply to DISC1-related CMI, i.e. CMI where DISC1 aggregates are implicated in the pathogenesis." (PMID 28275106, 2017). "Compared to proteins related to neurodegenerative diseases, the efficiency of transfer of DISC1 aggregates is lower." (PMID 28275106, 2017). "As previously shown for prion and other proteins involved in neurodegenerative diseases, we found that DISC1 aggregates can also transfer between cells through TNTs." (PMID 28275106, 2017). "Thus, it is unlikely the widespread Disc1 deletion has led to spurious results in previous sleep studies or that it alters sleep in mouse models of psychiatric or neurodegenerative diseases." (PMID 28720848, 2017). "Therefore, based on all the earlier findings and in comparison to the classical amyloids from neurodegenerative diseases, we estimate that the DISC1 monomer may be present in pM to nM concentrations within the cell." (PMID 34921141, 2021). "Since the potential role of aggregation of DISC1 in sporadic CMI is unknown, we investigated whether DISC1 undergoes aggregation in cell culture and could spread between neuronal cells in a prion-like manner, as shown for amyloid proteins in neurodegenerative diseases." (PMID 28275106, 2017). "We next investigated whether DISC1 aggregates can transfer between CAD cells in culture similarly to prion and prion-like proteins involved in neurodegenerative diseases." (PMID 28275106, 2017).
infection (5 papers, 2014 to 2025). The state of being infected such as from the introduction of a foreign agent such as serum, vaccine, antigenic substance or organism. "The percentage of CNPase immuno-positive cells decreased 96 hours after PDGF deprivation, following infection of DISC1-GFP-Adv (70.1±3.3%) compared with GFP-Adv (90.6±2.5%)." (PMID 24516667, 2014). "To test the role of DISC1 on NRG1-ErbB4 signalling, we then used lentiviral infection to express control or DISC1 shRNA in primary neuron cultures, followed by NRG1 treatment." (PMID 26656849, 2015).
neurodevelopmental disorder (5 papers, 2016 to 2026). A behavioral and cognitive disorder with onset during the developmental period that involves impaired or aberrant development of intellectual, motor, or social functions. "Its knockdown in Xenopus causes nuclear breakdown, apoptosis, and a striking loss of tissue architecture in the neural tube, but its associations with neurodevelopmental disorders, with which Disc-1 or TSC1 have linkages, are still unknown." (PMID 28125008, 2017). "It is unknown, however, whether PCNT, Disc1, and PCM-1, act independently or in an orchestrated manner in neurodevelopmental disorders." (PMID 28125008, 2017).
tumor (5 papers, 2016 to 2023). "DAXX and DISC1 have been associated with tumor invasion in previous studies; to our knowledge, DRD3 has not." (PMID 31850367, 2019). "DISC1 expression was negatively associated with phosphorylated (p-) GSK3β, but positively correlated with a more invasive tumor phenotype and predicted poor NSCLC patient prognosis." (PMID 29029423, 2017). "The present study assessed DISC1 expression in human NSCLC cell lines and tumor tissues, and evaluated relationships between DISC1 expression, clinicopathological features, and patient prognosis." (PMID 29029423, 2017). "DISC1 (P<0.01), tumor size (P=0.040), pathology grade (P<0.01) were correlated with patient survival status." (PMID 29029423, 2017). "To analyze the role of DISC1 in glioblastma carcinogenesis, we further assessed the effects of DISC1 on tumor growth in vivo." (PMID 27852062, 2016). "However, the mechanism of DISC1 regulating mitochondrial functions in tumor need to be clarified." (PMID 27852062, 2016). "And syncytin-1 can also affect various signal pathways to induce tumorigenesis, such as TRPC3, DISC1, SK3, Akt and Erk1/2, promoting the proliferation and invasion of tumor cells and improving the ability of distant metastasis." (PMID 37326913, 2023). "DISC1, β-catenin, Cyclin D1, and Ki-67 levels increased from well- to poorly-differentiated NSCLC tissues, and increased with increasing tumor grade." (PMID 29029423, 2017). "The number of cells required to generate at least one tumor sphere/well was calculated as 67.6 in DISC1 shRNA-1#-U251MG cells, 136.6 in DISC1 shRNA-2#-U251MG and 38.9 in control-shRNA-U25MG cells." (PMID 27852062, 2016).
brain disorder (4 papers, 2009 to 2020). A disease affecting the brain or part of the brain. "Defects of neuronal migration are linked with brain disorders and Disc1 has been suggested to play a role in this process." (PMID 33384588, 2020). "Such a model was previously used to evaluate effects of DISC1, a gene implicated in brain development and multiple brain disorders including autism." (PMID 30664616, 2019).
diseases of the central nervous system (1 paper, 2017). "A role for DISC1 in the cell cycle and apoptosis is observed in diseases of the central nervous system (CNS)." (PMID 28900388, 2017).
DISC1 also shares sentences with these, for which no sentence is quoted: autism spectrum disorder (5 papers); Intellectual disability (5); epilepsy (3); non-small cell lung carcinoma (3); attention deficit-hyperactivity disorder (2); endometrial carcinoma (2); Insulin resistance (2); alcoholism (1); amyotrophic lateral sclerosis (1); anxiety disorder (1); Autoimmunity (1); bacterial infections (1); brain cancer (1); Brunner syndrome (1); cannabis abuse (1); chronic fatigue syndrome (1); cognitive disorder (1); demyelinating disease (1); Disc Degeneration (1); Dravet syndrome (1); drug dependence (1); dyslexia (1); generalised anxiety disorder (1); Graves disease (1); hepatoma (1); hereditary spastic paraplegia (1); leukodystrophies (1); microcephaly (1); myocardial infarction (1); myotonic dystrophy (1).
A further 9 diseases each share a sentence with DISC1 in 1 paper.